CD58 (CD58 molecule)
Diseases named in the same sentence as CD58 in open-access papers (continued):
Sharing a sentence is not in itself a finding about the gene and the disease.
tumor (continued). "A genome-wide CRISPR library screening conducted in a coculture model involving the acute lymphoblastic leukemia cell line Nalm6 and CD19 CAR T cells revealed that CD58 loss in tumor cells affects optimal IS formation with CAR T cells, resulting in impaired CAR T-cell responses." (PMID 39349829, 2024). "The activation of CD58 may contribute to the upregulation of the Wnt/β-catenin pathway, a process that is implicated in promoting tumor self-renewal capabilities." (PMID 39156976, 2024). "Moreover, we observed that higher levels of CMTM6 and CD58 expression in tumor cells were associated with clinical benefit to ICB therapies." (PMID 37683639, 2023). "By comparing the functional outcome of individual or dual suppression of PD-L1 and CD58 in CMTM6-proficient and -deficient tumor cells in the T cell-tumor coculture, we revealed that CD58 expression is crucial for effective T cell-tumor cell interactions and response to PD-L1 inhibition." (PMID 37683639, 2023). "Additionally, studies using CD58 knockout mouse models have demonstrated reduced cytokine production and the loss of tumor‐killing ability in CAR T cells." (PMID 37904707, 2023). "The compromised T cell activation observed upon CMTM6 loss in tumor cells may be attributed to the reduced expression of CD58." (PMID 37683639, 2023). "Upregulated CD58 was strongly associated with poor histological grade and larger tumor size." (PMID 34193136, 2021). "Interestingly, concurrent loss of CD80/CD86 expression is found in CD58-deficient tumor cells." (PMID 39349829, 2024). "In vitro studies demonstrated that T/NK-mediated cytotoxicity could be restored by re-expression of wild-type CD58, suggesting the deficiency of CD58 restrains the recognition of tumor cells by T/NK cells and evades immune surveillance in a CD2/CD58-dependent manner." (PMID 34193136, 2021). "For T cell–tumour cell interactions, we observed several adhesion interactions, including between CD58 and CD2 and between ICAM1 and ITGAL." (PMID 41261135, 2026). "The absence of CD58 BiTE or the loss of interaction between CD2 and CD58 results in diminished TCE-β-mediated cytotoxicity, T cells activation, and anti-tumor efficacy, constituting a primary mechanism of BiTE resistance." (PMID 40365344, 2025). "Accordingly, tumor cells have also evolved other mechanisms, such as the downregulation of adhesion molecules (CD58 and LFA-1) to escape killing by cytotoxic immune cells." (PMID 41295262, 2025). "Research indicates that the IS established by the cooperation between CD58 of tumor cells and CD2 with CAR-T cells is essential for enhancing the cytotoxic efficacy of CAR-T cells." (PMID 40365344, 2025). "Suppression of CD58 has been found to stimulate the release of T cell-related chemokines and enhance adhesion molecule expression on tumor cell surfaces, indicating CD58’s role in reshaping the tumor immune microenvironment." (PMID 41438981, 2025). "Intriguing also was the fact that CD58+ dendritic cells (DCs) were detected in tumor-free niches, while the inactivated ones (CD58−) seemed to follow exhausted T-cells in plasma cell-rich niches." (PMID 40227595, 2025). "In contrast, as already indicated, activated CD8+ cytotoxic T-cells, M1 macrophages, and DCs with antigen presentation ability (CD58+) are retrieved in tumor-free niches or biopsy margins." (PMID 40227595, 2025). "Studies have demonstrated that CD58 expression in tumor cells influences tumor sensitivity to cytotoxic tumor-infiltrating lymphocytes (TILs) in a T cell receptor (TCR)-dependent manner." (PMID 41438981, 2025). "Previous studies have demonstrated that CD58 exhibits a dual role in either promoting or inhibiting tumor growth, depending on the specific tumor type." (PMID 40365344, 2025). "Coimmunoprecipitation analysis of tumor tissues revealed weakened CD2–CD58 interactions in the sh‐CD2 CTL group, as indicated by reduced CD58 band intensity." (PMID 40859981, 2025).
tumor (continued). "To evaluate CD58’s impact on tumor immune contexture, we analyzed its correlation with immune cell infiltration levels in TCGA pan-cancer cohorts." (PMID 41438981, 2025). "Immunohistochemical analysis demonstrated significantly higher expression of CD58 and PD-L1 in tumor tissues than in normal brain tissues." (PMID 41438981, 2025). "Mechanistically, CD58 protein can indirectly inhibit PD-L1 expression in tumor cells through the following pathway: CD58 protein interacts with and activates Lyn kinase." (PMID 40365344, 2025). "When tumor cells lose CD58 expression, they become resistant to tumor-infiltrating lymphocytes (TIL), thereby further promoting immune evasion." (PMID 40365344, 2025). "While the intrinsic costimulatory signal of CD2 in T cells remains important, leveraging its interaction with CD58 on tumors appears to be a pivotal mechanism in the regulation of tumor immunity and requires novel strategies." (PMID 39349829, 2024). "Recent studies have demonstrated the mechanism of CD58 downregulation in tumor cells, shedding light on the importance of CD58 as an intrinsic regulator of tumor cells 13,15." (PMID 39349829, 2024). "Taken together, these results suggest that the upregulation of HSPA4/ALKBH5/CD58 signaling axis in GC tumor cells negatively regulates the infiltration of CD8+ T cells in GC tumor mass." (PMID 38589927, 2024). "HSPA4 overexpression upregulates ALKBH5 via increasing its protein stability, leading to decrease of CD58 of tumor cells and increase of PD1/PDL1 axis, finally to impair the toxicity of CD8+ T cells and immune evasion of GC cells." (PMID 38589927, 2024). "We also observed that CD58 was downregulated in GC tumor tissues compared with normal gastric tissues in GEO cohort (GSE54129)." (PMID 38589927, 2024). "Correlation analysis results demonstrated that ALKBH5 correlated positively with HSPA4 while negatively with CD58 in GC tumor tissues." (PMID 38589927, 2024). "CD58 activates NK cells and cytotoxic T cells (CTL), and CD58 gene mutation or deletion induces tumor immune escape." (PMID 39240588, 2024). "To further determine the clinical significance of CD58, we used an objective IHC scoring method to assess and confirm the expression level of CD58 in tumor tissues." (PMID 37573318, 2023). "Conversely, when CD58 was overexpressed in both CMTM6-deficient and CMTM6-proficient tumor cells, their viability decreased to a comparable level after coculture with tumor-reactive T cells." (PMID 37683639, 2023). "Further study demonstrated that CD58 and sCD58 exert their pro-tumor effects by activating the AKT/GSK-3β/β-Catenin pathway." (PMID 37573318, 2023). "IHC analysis revealed widespread and largely overlapping expression of CMTM6 and CD58 in tumor cells in samples of both cancer types." (PMID 37683639, 2023). "Elevation of CD58 expression correlated with more satellite foci and vascular invasion, and poorer tumor-free and overall survival in HCC patients." (PMID 37573318, 2023). "The CD58-High expression group exhibited poor differentiation, larger tumor size, and vascular invasion." (PMID 37573318, 2023). "More importantly, we provide evidence that CD58 and sCD58 exert their pro-tumor effects by activating the AKT/GSK-3β/β-Catenin pathway." (PMID 37573318, 2023). "The tumor immune estimation resource (TIMER) algorithm was further employed to assess CD58 as an independent prognostic factor for OS in LGG patients." (PMID 37904707, 2023). "In this study, we found that CMTM6 (CKLF like MARVEL transmembrane domain containing 6) plays a key role in promoting the expression of both CD58 and PD-L1, two immune checkpoint ligands with opposing functions, in tumor cells." (PMID 37683639, 2023). "Functionally, the presence of CMTM6 and CD58 on tumor cells significantly affects T cell-tumor interactions and response to PD-L1–PD-1 blockade." (PMID 37683639, 2023).
tumor (continued). "Given the dual roles of CMTM6 in maintaining the cell surface expression of both CD58 and PD-L1, we sought to determine the relative importance of these two immune checkpoints with opposing functions in T cell-tumor cell interactions." (PMID 37683639, 2023). "In vitro studies have shown that the deficiency of CD58 limits the recognition of tumor cells by T/NK cells, leading to immune evasion in a CD2/CD58‐dependent manner." (PMID 37904707, 2023). "Supporting this, CD58 knockout abolished the differential response to tumor-specific T cells and PD-L1 blockade between CMTM6-proficient and -deficient cells." (PMID 37683639, 2023). "According to the survival analysis, HCC patients with CD58-High expression had substantially lower overall survival times (p = 0.0013) and tumor-free survival times (p = 0.0183) than those with CD58-Low expression." (PMID 37573318, 2023). "The CD2–CD58 interaction is an important component of immunological synapses, and CD58 expression on tumor cells is required both for NK cell and CTL-mediated cytolysis of DLBCL." (PMID 36765793, 2023). "Subsequently, Kaplan–Meier analysis showed the OS (p = 0.0003) and tumor-free survival (p = 0.0023) of patients with high CD58 expression were significantly inferior to those with low CD58 expression." (PMID 37573318, 2023). "These in vivo findings align with the in vitro data and suggest that the expression of CMTM6 in tumor cells contributes to the response to T cell-based immunotherapy by modulating CD58 expression levels." (PMID 37683639, 2023). "They highlight the critical roles of tumor-intrinsic CMTM6 and CD58 expression in modulating T cell-tumor cell interactions and their potential impact on T cell-based immunotherapy." (PMID 37683639, 2023). "CD58 is one of the T cell costimulatory molecules expressed by endothelial cells (ECs), and the CD2-CD58 interaction between T cells and ECs can facilitate recruitment of the circulating T cells to the site of the tumor." (PMID 35881486, 2022). "Next, we assessed CD58 expression in tumor cells by chromogenic IHC in 39 patients with relapsed or refractory LBCL treated with standard-of-care axi-cel for whom pretreatment tissue biopsy was available." (PMID 35881486, 2022). "In detail, we checked CD8+ T cells, CD68+ TAMs, and CD58+ NK cells in the tumor parenchyma (TP), stroma (TS), paracancerous tissue (PT), and nontumor tissue (NT)." (PMID 35150094, 2022). "In aggregate, these results show that the interaction between CD2 (T cells) and CD58 (tumor cells) promotes optimal antitumor cytolytic functionality." (PMID 35881486, 2022). "A recent conference abstract reporting on patients with DLBCL treated with axi-cel showed that tumor CD58 carried defects in 24% of the evaluated subjects." (PMID 35881486, 2022). "To explore the significance of the interaction of these receptors during interaction with tumor cells, we blocked either CD58 (on NALM-6 targets) or CD2/CD244 (on CAR T cells)." (PMID 35881486, 2022). "Next, we performed flow cytometry assays and confirmed that the number of degranulating CAR T cells was also reduced upon blocking CD58 on tumor cells." (PMID 35881486, 2022). "The univariate analysis indicated that poor OS of patients was relevant in high CD58 expression (p = 0.006), age (p = 0.007), gender (p = 0.026), tumor size (p = 0.045), TNM stage (p = 0.040) and perineural invasion (p = 0.013)." (PMID 34193136, 2021). "Frequent loss-of-function mutations were also observed for CD58, IGLL5, IRF1, LTB, MGA and VMP1 in blood cancers, implicating a potential tumour-suppressive role of these genes in the pathogenesis in this tissue type." (PMID 33420369, 2021). "CD58 is an important adhesion molecule expressed at distinct levels in a variety of normal cells and tumor cells." (PMID 34193136, 2021). "Regarding the roles of CD58 in tumor immunology, a looming but promising picture begins to come into sight from current studies." (PMID 34168659, 2021).
tumor (continued). "In the immunocompetent C57BL/6 mice model, rv-CD58-infected murine CRC cells significantly refrained tumor growth and induced antitumor immunity." (PMID 34168659, 2021). "The results showed that CD58 expression was positively linked to the monocyte marker CD86, neutrophil markers CD66b and CD11b, tumor-associated macrophage (TAM) marker CD68." (PMID 34193136, 2021). "These CD58-mediated possible mechanisms facilitate immune evasion and metastasis of tumor cells, although further in-depth studies are needed." (PMID 34168659, 2021). "In summary, the present study reveals that CD58 expression is upregulated in PDAC cancer tissues, which is associated with worse histological grade and larger tumor size and predicts a poor prognosis in PDAC patients." (PMID 34193136, 2021). "We have adopted this strategy and devised chimeric receptors where CD28-signaling domains were fused to the extracellular binding domains of either CD2, CD226 or TIGIT and thus can be engaged by CD58 or CD155 expressed on the tumor targets." (PMID 29707134, 2018). "The expression of MHC class I molecule, adhesion molecule ICAM-1 (CD54) and co-stimulation molecule LFA-3 (CD58) was significantly decreased in LN tumor samples from advanced stage III." (PMID 23284620, 2012). "High expression and interaction activity of CD2 and CD58 between CTLs and tumor cells in BCBM were identified, supporting downstream experimental validation and providing molecular evidence for the regulatory role of the CD2–CD58 axis in immune responses and tumor progression." (PMID 40859981, 2025). "Univariate and multivariate Cox proportional hazards regression analyses identified high CD58 expression (hazard ratio [HR] = 1.895, 95% confidence interval [CI]: 1.745–2.057, p < 0.001) and advanced tumor stage (HR = 1.326, 95% CI: 1.187–1.482, p < 0.001) as independent prognostic risk factors." (PMID 41438981, 2025). "Conversely, when CD58 is lost in tumor cells, CMTM6 switches to promoting PD-L1 expression." (PMID 40365344, 2025). "The staining intensity of CD58 and PD-L1 showed a positive correlation with advanced tumor grade." (PMID 41438981, 2025). "Second, could novel CAR constructs that integrate CD2 costimulatory domains while knocking out CD58 and/or CD54 surface molecules perform the dual functions of evading immune rejection and killing tumor cells that lack CD58 expression?" (PMID 40365344, 2025). "These two studies suggest that CD58 is also closely related to the tumor immune response in MM." (PMID 40365344, 2025). "These collective findings underscore the multifaceted and intricate role of CD58 in tumor immunity." (PMID 41438981, 2025). "Highly expressed CD58 correlates with an immunosuppressive tumor microenvironment." (PMID 41438981, 2025). "In addition, ALKBH5 is upregulated and CD58 is downregulated in tumor tissues with HSPA4 upregulation." (PMID 38589927, 2024). "Considering the cis-regulation between PD-L1 and CD80/CD86, tumor-intrinsic mechanisms might coregulate the expression of CD58, PD-L1, and CD80/CD86." (PMID 39349829, 2024). "In cases of treatment-resistant tumors exhibiting low CD58 levels, the deficiency in T-cell conjugation enables immune evasion by tumor cells, regardless of intact costimulation signals." (PMID 39349829, 2024). "Tumor-associated microglia downregulated CX3CR1 but upregulated CD112, CD58 and CD33." (PMID 38123840, 2024). "Tumors derived from CD58 stable-knockdown Huh7 cells grew more slowly and were significantly smaller than tumors from control Huh7 cells, as determined by the quantification of tumor volume and tumor weight." (PMID 37573318, 2023). "To test this hypothesis, we cocultured wild-type and CMTM6-knockout tumor cells with tumor-specific T cells in the presence of PD-L1- or CD58-blocking antibodies, or their combination." (PMID 37683639, 2023). "Indeed, 79.7% (55/69) of HCC patient tissues showed higher CD58 protein expression levels than adjacent non-tumor tissues." (PMID 37573318, 2023).
tumor (continued). "Moreover, we individually quantified the protein expression levels of CMTM6 and CD58 on tumor cells based on the IHC analysis." (PMID 37683639, 2023). "Additionally, when CD58 was inhibited, the enrichment of CMTM6-deficient tumor cells by CAR-T treatment was diminished." (PMID 37683639, 2023). "In contrast, PD-L1 loss in tumor cells did not result in an obvious increase in the levels of CD58 or CMTM6/CD58 interactions." (PMID 37683639, 2023). "Notably, analysis of human tumor biopsies showed that both CMTM6 and CD58 are commonly expressed on tumor cells, and that their expression levels are positively correlated." (PMID 37683639, 2023). "Furthermore, PD-L1 inhibition enhanced the killing of tumor cells by T cells, while, on top of that, inhibition of CD58 significantly rescued the tumor cells." (PMID 37683639, 2023). "Consistent with this, we observed that elevated CD58 expression on pretreatment tumor samples in patients with relapsed or refractory large B cell lymphomas treated with CD19-specific CAR T cell therapy was associated with complete clinical response and survival." (PMID 35881486, 2022). "Taken together, these studies support the notion that the CD58 molecule plays a vital role in tumor cell biology and highlight that regulation of the adhesion molecule CD58 on the surface of tumor cells may be a promising immunotherapeutic strategy." (PMID 34168659, 2021). "In addition to mediating T immune response in solid tumors, several recent reports have demonstrated that CD58 molecule can serve as stem cell marker or an oncogene in tumor initiation and progression." (PMID 34168659, 2021). "Furthermore, CD58 can promote the self-renewal of tumor-initiating cells by upregulating the Wnt/β-catenin pathway." (PMID 29930758, 2018). "In addition, activated CD58 upregulates the Wnt pathway, and knockdown of CD58 impairs sphere formation and tumor growth." (PMID 26943771, 2016). "Importantly, mutations potentially contributing to immune evasion have been described in HLA-A in a small percentage of LUSC and of B2M and CD58 in other tumor types." (PMID 24162015, 2013). "Importantly, in both scenarios, manipulating CD58 levels through knockout and overexpression eliminated the difference in T cell activation between cocultures with either CMTM6-proficient or CMTM6-deficient tumor cells." (PMID 37683639, 2023). "In addition, knockdown of CD58 significantly impaired sphere formation and prevented tumor growth." (PMID 37836662, 2023). "In addition, it was also shown that knockdown of CD58 significantly impaired tumor growth." (PMID 37836662, 2023). "Notably, CD58 is frequently downregulated not only in large B-cell lymphomas but also in multiple other lymphoid malignancies suggesting that this tumor cell-intrinsic resistance mechanism might be frequent." (PMID 36189315, 2022). "The costimulatory signaling of CD58 facilitates CTL activation, proliferation, and cytotoxicity, while CD58 loss may contribute to a reduction in the recognition and adhesion of T/NK cells to tumor cells in tumor microenvironment." (PMID 34193136, 2021). "Besides, CD58 silence notably dampened sphere formation and tumor growth." (PMID 34168659, 2021). "As an immune-related molecule, CD58 may play a role in tumor immune microenvironment." (PMID 34193136, 2021). "Notably, upregulation of CD58 expression in tumors appears to contradict its role as a T cell costimulatory molecule, as high expression of CD58 on the surface of tumor cells may be more readily recognized and killed by T cells." (PMID 34168659, 2021). "Specifically, when tumor cells highly express CD58, CMTM6 binds to CD58 and promotes its stability via endosomal recycling, thereby inhibiting PD-L1 protein expression." (PMID 40365344, 2025). "EZH2 mutation has also been reported to repress the expressions of CD58, PRAME, and cancer-testis antigen, and to inhibit anti-tumor effects of T cells and macrophages." (PMID 36765793, 2023).